ENSG00000200733
Synonyms: LOC124903257
Gene: Small nucleolar RNA gene on chromosome 13 (89,837,170 to 89,837,237, forward strand). Ensembl gene ENSG00000200733.
Gene Ontology:
Biological process: RNA processing
Cellular component: nucleolus
Homologues: Orthologues: mouse Gm22980 (79% identical), rat Snord38b (79% identical). Paralogues in human: SNORD38C (87% identical), SNORD38B (84% identical), SNORD38D (81% identical), SNORD38A (68% identical).